SMAD4 (SMAD family member 4)
Diseases named in the same sentence as SMAD4 in open-access papers (continued):
Sharing a sentence is not in itself a finding about the gene and the disease.
tumor (continued). "On the other hand, SMAD4 serves as a tumor-suppressor and mediates cell cycle arrest as well as induced apoptosis in a SMAD4-dependent TGF-beta signaling pathway." (PMID 28053288, 2017). "In the late stage of tumorigenesis, TGF-β promotes tumor growth by a combined effect of Smad4-dependent and -independent effects on EMT." (PMID 28067794, 2017). "Using immunohistochemistry, we examined SMAD4 expression in tumor tissue of 143 aPC pts treated within completed prospective clinical and biomarker trials." (PMID 28534865, 2017). "In this work, we concurrently deleted Smad4 and the tumor suppressor and endogenous Wnt/beta-catenin inhibitor adenomatous polyposis coli (Apc) in luminal prostate cells in mice." (PMID 29113300, 2017). "TGF-beta/SMAD4 signaling regulates tumor development because of its effects on growth arrest and induced apoptosis." (PMID 28053288, 2017). "SMAD4, a tumor suppressor, is frequently reduced in cancer tissue and is associated with evolving neoplasms." (PMID 28199217, 2017). "When the clinicopathological features were compared according to SMAD4 and RUNX3 expression status, we found SMAD4 loss was associated with increased tumor size (p = 0.030), higher pN stage (AJCC 8th ed)." (PMID 29100342, 2017). "For example, blockade of TGF‐β1 or αvβ6 in a genetically engineered KRAS PDAC mouse model was found to accelerate disease progression in Smad4‐expressing tumours." (PMID 28608476, 2017). "Our study is the first to show that miR-205 functions as a tumor-promotive miRNA through directly binding to SMAD4 and PTEN in OC." (PMID 28145479, 2017). "First identified at the 18q21 locus in 1996, Smad4 and has attracted interest as a candidate tumor suppressor gene for 18q21 allelic imbalance." (PMID 28423626, 2017). "The tumour suppressor SMAD4 located on chromosome 18q21.1 was frequently affected by gene copy loss (53%)." (PMID 28120820, 2017). "In those investigations, SMAD4 was mainly analyzed in patients with resectable disease, most likely because tumor tissue is easily available in such patients." (PMID 28534865, 2017). "There is a growing appreciation for the notion that metastasis-regulating genes, such as KISS1, BRMS1, NME1 or SMAD4, exert their effects at both the tumor and TME level." (PMID 29050279, 2017). "TGF-beta/SMAD4 signaling pathway regulates tumor development through mediating growth arrest and inducing apoptosis." (PMID 28053288, 2017). "SMAD4 was initially identified as a tumor suppressor and central mediator of transforming growth factor (TGF)‐β signaling." (PMID 28256094, 2017). "miR- 224 also plays an oncogenic role in HCC tumor formation and hepatoma cell migration through silencing its target gene named SMAD Family Member 4 (Smad4)." (PMID 28392501, 2017). "We believe SENP1 silencing leads to the increased SMAD4 levels due to improved stability of SMAD4 in the tumor cells." (PMID 28417919, 2017). "The positive expression of Smad4 is higher than that before Kuijie Granule treatment (P < 0.01), which shows that Kuijie Granule helps in increasing the positive expression of Smad4 which is very important for inhibiting the development of UC to tumor." (PMID 27019660, 2016).
tumor (continued). "The reduction of SMAD4 is found in tumors, 67 % of the adjacent non-tumor tissues from HNSCC patients also show more than 50 % SMAD4 reduction." (PMID 27391030, 2016). "The regulatory capacity of miR-146b-5p on tumor invasion, possibly through SMAD4 and the impairment of TGF-β signaling, shows its important role on PTC aggressiveness and invasiveness." (PMID 26883911, 2016). "Some studies have demonstrated that Smad4 plays tumor suppressive functions in most types of human cancers." (PMID 26817584, 2016). "Smad4, locating at chromosome 18q21, was first identified as a tumor suppressor gene in pancreatic cancer." (PMID 27595937, 2016). "We next investigated the efficacy of Smad4 over-expression against tumor growth, metastasis, and angiogenesis in vivo." (PMID 27595937, 2016). "Collectively, these results revealed the tumor suppressive roles of Smad4 in regulating the growth, invasion, and angiogenesis of NB cells." (PMID 27595937, 2016). "Subsequently, we performed immunohistochemistry on the resected tumor specimens of the mice to evaluate the expression of SMAD4 in vivo." (PMID 26726879, 2016). "As a tumor suppressor miRNA, miR-34a acts as a tumor suppressor by targeting Smad4 in proneural subtype glioblastoma." (PMID 26563372, 2016). "To elucidate the immune evasion mechanisms of SCCs, we established a transplanted tumor model using tumor cells derived from primary K15.KrasG12D.Smad4−/− SCCs (hereafter referred to as KRS-SCCs)." (PMID 27835902, 2016). "The result showed that SMAD4 was strongly stained in the nuclei of tumor cells when the mice were treated with a single administration of GEM." (PMID 26726879, 2016). "Smad4 is an important tumor suppressor involved in TGF-β/BMP signaling, and patients with low expression of Smad4 tended to exhibit more poorly differentiated tumors, a higher risk of recurrence and shorter overall survival." (PMID 27588500, 2016). "In contrast, SMAD4 was weakly stained in the nuclei of tumor cells when the mice were treated with GEM and vorinostat." (PMID 26726879, 2016). "Cells tumor of metastatic pancreatic adenocarcinoma show positive immunohistochemical staining for SMAD4, CK19, CK7, CK18, CK20 and CA19/9." (PMID 26097628, 2015). "To confirm the effect of the TβRI inhibitor, we evaluated the phosphorylation of Smad2 and Smad4, which are downstream targets of the receptor, by immunohistochemistry in tumor samples from allergic mice and allergic mice treated with the inhibitor." (PMID 26076663, 2015). "The positive expression rate of TβRII and Smad4 was also reduced in the patients with higher tumor stages." (PMID 25452807, 2015). "According to this study, TOB1 interacted with another tumor suppressor protein, SMAD4, and enhanced the binding of SMAD4 to the SMAD binding element (SBE) located on the promoter region of IL-2, thereby dampening IL-2 transcription." (PMID 26694352, 2015).
tumor (continued). "In contrast, the phosphorylation of both Smad2 and Smad4 was significantly reduced in the tumors treated with the inhibitor (OVA + tumor + Inh), indicating that blocking TβRI inhibits the TGF-β signaling cascade." (PMID 26076663, 2015). "SMAD4, the key components of TGF-β signaling transduction pathway, was found as the frequently mutated tumor suppressor genes in human tumors." (PMID 26598317, 2015). "SMAD4 is a co-factor that facilitates gene transcription and tumor suppression through the TGF-beta signaling pathway." (PMID 25714017, 2015). "For example, multiple studies have shown that TGF-β inhibition promotes PDA progression, whereas others have shown that in certain tumors SMAD4 facilitates epithelial to mesenchymal transition and tumor growth." (PMID 26172047, 2015). "MYH9, 10 and 14 mutant tumors also exhibited mutational inactivation and/or copy loss of commonly altered tumor suppressors CDKN2A (p16), FAT1, or NOTCH1, and infrequently altered TGFβ pathway components, TGF-B-R2 or SMAD4." (PMID 26369831, 2015). "The phenotype observed fits well with previous models in which mice with intact Smad4 signalling display a TGFβ-dependent, EMT-associated tumour growth." (PMID 26220524, 2015). "A significant low level IHC scores of SMAD4 was examined in tumor tissues compared to those in corresponding non-tumor tissues (detailed IHC evaluation listed in the Materials and Methods)." (PMID 26019136, 2015). "GISTIC analysis defined significant common regions of amplification and deletion that harbour multiple oncogenes (for example, MYC and CCND1) and tumour suppressors (for example, SMAD4 and CDKN2A)." (PMID 25855536, 2015). "Although Smad4 is generally considered to be a tumor suppressor gene, it is indispensable in the regulation of the TGF-β-inducible EMT." (PMID 26530532, 2015). "Another limitation is the difference between the results of miR-301a-3p or SMAD4 manipulated animals or cell lines and that of clinicopathological variables such as perineural invasion, lymphatic invasion or tumor volume." (PMID 26019136, 2015). "Given the results of our study, it is likely that the role of IMP3 in facilitating metastatic potential is more pronounced in DPC4/Smad4-negative tumour cells." (PMID 25886367, 2015). "Smad4-dependent TGF-β signaling is common during tumor development and progression and can modulate cell proliferation, affect cell motility, regulate the epithelial-mesenchymal-transition (EMT) process and affect sensitivity to clinical therapy." (PMID 25333693, 2014). "SMAD4 acts as a tumor suppressor to inhibit β-catenin and targets the TGFβ signaling pathway to control epithelial cell growth." (PMID 24943349, 2014). "In contrast to early carcinogenesis, the presence of SMAD4 seems to be important for the metastatic potential of PDAC tumour cells in vivo." (PMID 24393789, 2014). "Smad4, a tumor suppressor gene located on chromosome 18q21.1, was recently reported to predict clinical outcomes in some cancers." (PMID 25333693, 2014). "By associating and deacetylating Smad4, SIRT1 enzyme can influence MMP7 expression, MMP enzyme activity, and consequently, cell migration, invasion, and tumor metastasis in OSCCs." (PMID 25424420, 2014). "The TGF-β/SMAD4 dependent barrier to tumor progression is destructed in metastatic PCa through involvement of transcription factor COUP-TFII/NR2F2." (PMID 25277175, 2014). "Mice knockout for TGFβ1, TGFβRII, or SMAD4 genes are more likely to have spontaneous tumour development and excessive inflammatory responses, confirming the tumour suppressor properties of the TGF-β pathway." (PMID 24393789, 2014). "As a tumor suppressor, SMAD4 has been extensively analyzed, but reports of its function in EMT have been contradictory." (PMID 25264609, 2014). "Mutation of DPC4 leads to loss of Smad4 expression or function and therefore loss of TGF-β tumor suppressor activity." (PMID 24340014, 2013).
tumor (continued). "Perhaps, most importantly, the classical SMAD4 tumour suppressor deletion and oncogenic MYC gain were both observed within deleted and gained FMCR respectively." (PMID 24367615, 2013). "Among the putative target genes, Smad4, an important tumor suppressor involved in TGF-β/BMP signaling, was shown to contain a conserved putative miR-130a/301a/454 target site based on TargetScan prediction." (PMID 23393589, 2013). "In earlier OL stage the higher SMAD4 reflected the protection reaction because of the dysplastic proliferation of the epithelial cells, while in the later OSCC stage the lower SMAD4 reported the dysfunction of the tumor suppress gene." (PMID 23826135, 2013). "The lower SMAD4 expression in OSCC tissues was in accordance with the other studies which showed that SMAD4 was a tumor suppressor in OSCC." (PMID 23826135, 2013). "Altogether, these findings are congruent to previous work examining the role of Smad4 in repressing tumor growth, metastasis, cellular invasion in established PDAC cell lines such as BxPC3, Hs766T, and Panc1." (PMID 24386371, 2013). "In HNSCC, loss of heterozygosity at SMAD4 gene region was observed in 30%–50% of the tumors, suggesting a tumor suppressor role of SMAD4." (PMID 23826135, 2013). "Concerning Tregs, one of the major suppressors of anti-tumour immune surveillance, Smad4-independent development of Tregs in our model and Smad2/3-independent development of nTregs in vivo indicate that Treg development is Smad-independent." (PMID 24127404, 2013). "Pharmacological inhibition with TGF-β receptor kinase inhibitors or tumour specific Smad4 knockdown disturbed invasion and metastasis in the zebrafish xenograft model and closely mimicked the results we obtained with these cells in a mouse metastasis model." (PMID 24196484, 2013). "Deregulation in TGF-β/SMAD4 signaling leads to epigenetic silencing of a putative tumor suppressor, RunX1T1, during ovarian carcinogenesis." (PMID 22943793, 2012). "In a genetically engineered mouse model, SMAD4 mutations were shown to stimulate the progression of KRAS activated precursor lesions to pancreatic malignancies, indicating that SMAD4 function can inhibit the oncogenic progression of neoplasms." (PMID 24213498, 2012). "Lymph node ratio <0.2 (p = 0.004), tumor free resection margins (p = 0.044) and Smad4 expression (p = 0.004) were the only independent prognostic variables in the multivariate analysis." (PMID 22351431, 2012). "Tumor cells can evade the anti-tumor effects of TGF-β by acquiring alterations in the TGF-β signaling pathway, such as mutations in receptors or Smad4 and upregulation of inhibitory Smads." (PMID 23049692, 2012). "Overexpression of Smad4 has been reported to diminish β-catenin signaling, and, hence, prevent tumor progression." (PMID 22710759, 2012). "The analysis included the variables lymph node status, LNR, resection margin, tumor stage and Smad4 expression." (PMID 22351431, 2012). "Reduced expression or loss of SMAD4 protein leads to decreased ability to bind DNA; SMAD4 inactivation is involved in the acquisition of a more aggressive tumor." (PMID 22943793, 2012). "Recent studies reported that SMAD4/DPC4 has a TGF-β-independent function as tumour suppressor in cooperation with β-catenin/Lef to regulate target gene expression." (PMID 21772334, 2011). "In this study, Smad4 was expressed in most of the normal samples (96%) but lost in 40% of tumor samples." (PMID 22195733, 2011). "SMAD3 and SMAD4 are the key signaling proteins of the transforming growth factor-β (TGF-β) pathway and have been implicated to have tumor suppressive effects in the pathogenesis of breast and other cancer types." (PMID 21835029, 2011). "Mothers against decapentaplegic homologue 4 (SMAD4), expressed ubiquitously in different human organ systems, was initially isolated as a tumor suppressor gene on chromosome 18q21.1 in pancreatic ductal adenocarcinomas." (PMID 21791112, 2011).
tumor (continued). "SMAD3 and SMAD4 mRNA expression levels were found to be significantly elevated in the tumor tissues compared to normal tissues for four of five probes (> 5-fold average increase, P < 0.05) and one of two probes (> 10-fold increase, P < 0.01)." (PMID 21835029, 2011). "In non-small-cell lung carcinoma, immunohistochemistry revealed that SMAD4 was expressed at high level in normal broncho-tracheal epithelium, but at low level in tumor tissues, and closely correlated with tumor lymph node metastasis." (PMID 21791112, 2011). "For example, mutations or loss of expression of tumour-suppressor proteins expressed by tumour epithelial cells such as Smad4, or patterns of stromal fibroblast-expressed proteins such as Sparc have been shown to predict outcome." (PMID 21448168, 2011). "The difference in Smad4 protein levels in tumor tissue as compared to normal pancreatic tissue was highly significant on Fisher's exact test (two tailed p value = 0.0001)." (PMID 22195733, 2011). "In tumor samples, out of 15 Smad4 positive cases, 10 showed low and 5 showed moderate Smad4 protein expression." (PMID 22195733, 2011). "There was a significant difference in protein expressions of Smad4 (p = 0.0001), Smad6 (p = 0.0015) and Smad7 (p = 0.0005) protein in tumor as compared to paired normal samples." (PMID 22195733, 2011). "Smads are the key intracellular mediators of transcriptional responses to TGF-β signaling, and among these Smad4 is the pivotal factor of the TGF-β pathway as it functions as a key tumor suppressor." (PMID 20565773, 2010). "We here present data showing that tumor cell responses to TNFα and to the combination of TNFα and TGFβ critically depend on Smad4." (PMID 20307265, 2010). "In this novel study, we found that SMAD4 gene aberrations are the common event in CRC development but play a differential role in the progression of CRC in higher tumor grade (C + D)." (PMID 20565773, 2010). "The tissue restriction of alterations in SMAD4/DPC4, as in many other tumor-suppressor genes, emphasizes the complexity of rate-limiting checkpoints in human tumorigenesis." (PMID 20565773, 2010). "Consistent with their function as tumor suppressors, deletion of SMAD4 or TGFβRII in the pancreatic epithelium in mice accelerates KRASG12D-initiated tumors." (PMID 24281218, 2010). "Here, we address Smad4 dependent effects of the prominent inflammatory cytokine TNFα on tumor cells." (PMID 20307265, 2010). "In other words we can say that the tumor which has SMAD4 mutant status is also likely to have KRAS gene mutant status." (PMID 20565773, 2010). "Another salient feature of the mutations found in this study was the deletion of AGACA pentamer in exon 9 of the SMAD4 gene in one tumor tissue from a Familial Adenomatous Polyposis case." (PMID 20565773, 2010). "It has been shown that Smad2, Smad3 and Smad4 all have physical interactions with ERα and that Smad4 acts as a transcriptional co-repressor for ERα and inhibits tumor growth by inducing apoptosis in ERα-positive cells." (PMID 19943940, 2009). "Mis-regulated genes identified here in Smad4 mutant ES cells and those previously characterised in screens analysing Smad4 targets in tumour cell lines show surprisingly little overlap." (PMID 19849841, 2009). "Smad4, originally discovered as a tumour suppressor gene, shares overall structural features with the R-Smads." (PMID 19849841, 2009). "Further investigations are needed to identify the target genes that are specifically regulated by R-Smads and/or Smad4, especially in the context of tumor cells." (PMID 19943940, 2009). "Molecular mechanisms and target genes through which Smad4 mediates its tumor suppressor function are still incompletely understood." (PMID 18664273, 2008).